GAB2 (GRB2 associated binding protein 2)
Diseases named in the same sentence as GAB2 in open-access papers (continued):
Sharing a sentence is not in itself a finding about the gene and the disease.
breast carcinoma (continued). "Previous studies and the current one showed that the Shp2 expression pattern was correlated with the protein level of ER in breast tumors, and that the expression of Gab2 (Shp2's pattern protein) was induced by E2 in breast cancer cells." (PMID 25048202, 2014). "Gab2 is overexpressed in estrogen receptor-positive cells, and a subset of breast cancers is driven by Gab2 overexpression coupled with RTK ErbB2 (also known as Neu or HER2) receptor signaling." (PMID 23431498, 2013). "Firstly, Gab2 is frequently over-expressed in human breast cancer cell lines and primary tumours and becomes tyrosine phosphorylated in these cells in response to EGF, insulin and bFGF stimulation." (PMID 19737390, 2009). "Despite these discrepancies, it is clear that Gab2 co-operates with Neu to promote the development or progression of mouse mammary tumours." (PMID 19737390, 2009). "In breast cancer, the GAB2 phosphorylation of T508, S185 and Y373 sites is higher in normal tissue." (PMID 38995439, 2024). "GAB2 had abnormal expression in breast cancer and cell lines." (PMID 38995439, 2024). "The EMSY, PAK1, RSF1, and GAB2 genes are located within the 11q13/14 breast cancer amplicon." (PMID 28391240, 2017). "Moreover, in breast cancer, leptin induces Src/Gbr2/Gab2/STAT3 activation and Rac-1 crosstalk to facilitate VEGF/VEGFR2 activation." (PMID 27472371, 2016). "The small interfering (si)RNA-mediated silencing of Gab2 in breast cancer lines exhibiting Gab2 amplification has suggested a dependency on Gab2 for cell proliferation, cell-cycle progression, survival and invasion, which is likely mediated through altered PI3K and MAPK signaling." (PMID 26095858, 2015). "Gab2, which encodes a scaffolding adapter protein known to regulate EGF receptor signaling through ERK, is critical for the phagocytic function of macrophages, and was recently shown to promote breast cancer invasion and metastasis." (PMID 25674539, 2015). "Furthermore, deletion of Gab2 delays migration of mouse mammary tumors generated using breast cancer cell lines and this defect can be fully restored by reintroduction of a plasmid expressing Gab2." (PMID 22216034, 2012). "Indeed, the original study on Gab2 in breast cancer demonstrated that the expression of both Gab2 mRNA and protein was induced by estradiol in an ER-dependent manner." (PMID 19737390, 2009). "In agreement with the original findings by Lynch and Daly (2002), a recent study comparing murine breast cancers driven by an ErbB2 transgene alone or in combination with an constitutively activated AKT transgene showed that the phosphorylation of Gab2 at Y452 was dramatically reduced in the latter." (PMID 19737390, 2009). "Furthermore, Gab2 expression is estrogen-regulated in hormone-responsive breast cancer cells and studies in various cellular systems have revealed that Gab2 and Gab3 are up-regulated during cellular differentiation processes." (PMID 19737390, 2009). "Although it is uncertain at this stage as to whether such high Gab2 expression levels occur in breast cancers, these data underscore the oncogenic potential of Gab2 and suggest that Gab2, although being a weak oncogene by itself, might be an important cooperation partner of other oncoproteins." (PMID 19737390, 2009). "In contrast, miR-486 inhibits cell proliferation and invasion through repressing GAB2, PIK3R1, Snail, neuropilin-2, CDK4, or PIM-1 in non-small-cell lung cancer, colorectal cancer, prostate cancer, hepatocellular carcinoma, and breast cancer cells." (PMID 32155804, 2020). "Although Gab2 has a modest impact on mammary tumor initiation/growth, Gab2 deletion leads to impaired ERK activity and attenuated mammary tumor metastasis." (PMID 26754532, 2016).
breast carcinoma (continued). "Here, the authors could show that Gab2 expression levels were elevated in mammary tumours induced by the Neu (ErbB-2) oncogene suggesting that an oncoprotein-distorted signalling network alone might be sufficient to up-regulate the expression of Gab2, e.g. via increased E2F activity." (PMID 19737390, 2009). "For HER2 subtype, confirms that agents targeting GAB2 or GAB2-dependent pathways may be useful for treating breast tumors that overexpress HER2, and thus we include GAB2 as a correlated gene for HER2 type breast cancer." (PMID 31874642, 2019). "Recent studies have shown several members of let-7 family were diminished expression in breast cancer compared with normal breast tissues, and inhibited the breast cancer cell migration and invasive ability through regulating HMGA2, Lin28, GAB2, FN1, MAPK and MMPs." (PMID 25884389, 2015). "Gab2 is essential for epidermal growth factor (EGF) signaling and breast cancer cell proliferation." (PMID 26095858, 2015). "Gab2 amplification has been seen in nonhematopoietic cancers such as breast cancer cell lines." (PMID 22216034, 2012). "Amplification of GAB2, independent of CCND1, has been observed in breast carcinoma samples." (PMID 28391240, 2017).
ovarian carcinoma (27 papers, 2013 to 2025). A malignant neoplasm originating from the surface ovarian epithelium. "In ovarian cancer, systematic evaluation of candidate genes from this region identified GAB2 as the likely oncogenic driver." (PMID 40773291, 2025). "Our research and previous reports found that GAB2 is highly expressed in ovarian cancer, gastric cancer, and prostate cancer." (PMID 38995439, 2024). "In contrast, SHP2 inhibition specifically reduced ERK1/2 activity, ovarian cancer cells expressing GAB2, and their ability to proliferate." (PMID 38504984, 2024). "We also found that Gab2 can mediate the proliferation, metastasis and chemosensitivity of ovarian cancer by regulating the expression of CrkII." (PMID 37085900, 2023). "To further explore the interaction between Gab2 and CrkII, we conducted immunocoprecipitation in ovarian cancer cells." (PMID 37085900, 2023). "As reported, the expression of Gab2 was up-regulated in many malignant tumors, such as breast cancer, ovarian cancer, liver cancer and melanoma." (PMID 37085900, 2023). "This study explored the expression of Gab2 and CrkII in ovarian cancer through tissue chips for the first time, and analyzed their clinical significance." (PMID 37085900, 2023). "Then, we analyzed the possible molecular mechanism of Gab2 on the biological behavior of ovarian cancer cells." (PMID 37085900, 2023). "Our previous experimental results also showed that the expression of Gab2 was up-regulated in ovarian cancer." (PMID 37085900, 2023). "Immunohistochemical results showed that the expression of Gab2 was increased in 74 ovarian cancer tissues, while 28/119 cases had strong/moderate staining in adjacent tissues." (PMID 37085900, 2023). "In this study, the expression of Gab2 and CrkII in ovarian cancer tissue chip were detected by immunohistochemistry for the first time." (PMID 37085900, 2023). "Although the role of Gab2 in ovarian cancer has been rarely reported, more studies are needed to explore the possible molecular mechanism of Gab2 mediating malignant behavior of tumor cells." (PMID 37085900, 2023). "Grb2-associated binding protein 2 (GAB2), a scaffolding protein necessary for ovarian cancer peritoneal metastasis, is overexpressed in cancers." (PMID 37377954, 2023). "To illuminate the effect of Gab2 on the biological behavior of ovarian cancer cells, we transfected siRNA or overexpressed virus on A2780 and SKOV3 cells." (PMID 37085900, 2023). "Standard chemotherapy employs GAB2 as a potential gene target in treatment of GAB2-driven ovarian cancer." (PMID 34764329, 2021). "Overexpression of GAB2 in ovarian cancer cells promotes tumour growth and angiogenesis by upregulating the expression of CXCL1, CXCL2 and CXCL8, which are IKKβ-dependent." (PMID 31895688, 2020). "Most importantly, the expression of miR-125b and Gab2 mRNA was negatively correlated in ovarian cancer specimens." (PMID 28881624, 2017). "It is well documented that Gab2 is involved in human tumorigenesis, especially in leukemia, breast and ovarian cancers." (PMID 28420432, 2017). "Overexpression of Gab2 promotes tumor angiogenesis by increasing the expression of multiple chemokines in ovarian cancer, and Gab2 also promotes the growth of cancer cells in lung cancer and glioma." (PMID 28842424, 2017). "Inhibition of IKKβ augmented the efficacy of PI3K/mTOR inhibition in suppressing clonogenic growth of ovarian cancer cells with GAB2 overexpression." (PMID 26657155, 2016). "Suppression of GAB2 in all three ovarian cancer cell lines decreased the mRNA levels of CXCL1, CXCL2 and CXCL8." (PMID 26657155, 2016). "Taken together, these findings suggest that overexpression of GAB2 in ovarian cancer cells promotes tumor growth and angiogenesis by upregulating expression of CXCL1, CXCL2 and CXCL8 that is IKKβ-dependent." (PMID 26657155, 2016).
ovarian carcinoma (continued). "Ovarian cancer cells overexpressing GAB2 are dependent on GAB2 for activation of the phosphatidylinositol 3-kinase (PI3K) pathway and are sensitive to PI3K inhibition." (PMID 26657155, 2016). "Overexpression of GAB2 upregulated the secretion of several chemokines from ovarian cancer cells, including CXCL1, CXCL2 and CXCL8." (PMID 26657155, 2016). "We next examined the expression levels of GAB2 and these chemokines in 50 ovarian cancer cell lines characterized by the cell line encyclopedia project." (PMID 26657155, 2016). "We found that overexpression of GAB2 in ovarian cancer cells upregulated expression of multiple chemokines, including CXCL1, CXCL2 and CXCL8 that exhibited mitogenic and pro-angiogenic activities." (PMID 26657155, 2016). "Specifically, we found that suppression of GAB2 by inducible small hairpin RNA in ovarian cancer cells inhibited tumor cell proliferation, angiogenesis and peritoneal tumor growth in immunodeficient mice." (PMID 26657155, 2016). "We obtained evidence that overexpression of GAB2 in ovarian cancer cells increased expression of multiple chemokines." (PMID 26657155, 2016). "We showed that inhibition of IKKβ by both genetic and pharmacological means effectively reduced the transcription of CXCL1, CXCL2 and CXCL8 in GAB2-overexpressing FTSECs and ovarian cancer cells." (PMID 26657155, 2016). "Taken together, these findings not only support our conclusion that GAB2 is a frequently altered oncogene in ovarian cancer but also assign GAB2 as an inducer of tumor angiogenesis important for disease development and progression." (PMID 26657155, 2016). "GRB2-associated-binding protein 2 (Gab2), a member of the Gab/DOS family of scaffolding adapter proteins, is highly expressed in ovarian cancer." (PMID 26356073, 2015). "Conversely, silencing of Gab2 inhibits the migration and invasion, and positively regulates E-cadherin expression in ovarian cancer cells with high-Gab2 expression." (PMID 26095858, 2015). "However, in ovarian cancer, GAB2 phosphorylation of T353 and S172 in tumor tissues were significantly higher than those in normal tissues." (PMID 38995439, 2024). "Furthermore, SHP2 inhibitors and PI3K inhibitors combine to prevent the growth and survival of GAB2-overexpressing ovarian cancer cells both in vitro as well as in vivo." (PMID 38504984, 2024). "Gab2 regulates the biological behaviors of ovarian cancer cells through CrkII." (PMID 37085900, 2023). "In addition, we found that there was a positive correlation between the expression of Gab2 and CrkII in ovarian cancer(r = 0.589, P < 0.001)." (PMID 37085900, 2023). "Immunohistochemistry revealed that high expression of Gab2 and CrkII in ovarian cancer." (PMID 37085900, 2023). "In the previous study, we found that Gab2 was increased in ovarian cancer tissues." (PMID 37085900, 2023). "Immunohistochemistry was used to detect the expression of Gab2 and CrkII in ovarian cancer." (PMID 37085900, 2023). "In addition, studies had shown that Gab2 was expressed in a stage, grade and histological type dependent manner in ovarian cancer and was related to progression free survival in patients." (PMID 37085900, 2023). "The expression of Gab2 and CrkII increase in ovarian cancer." (PMID 37085900, 2023). "The higher expression of Gab2 and CrkII predict the poor prognosis of patients with ovarian cancer." (PMID 37085900, 2023). "miRNAs that inhibit Gab2 have also been found in ovarian cancer and human renal cell carcinoma." (PMID 36421826, 2022). "Thus, miR-200c mimic or CD44 targeted therapy should improve the treatment of ovarian cancer with Gab2 overexpression after the failure of standard therapies." (PMID 34946546, 2021). "Growth factor receptor bound protein 2-associated protein 2 (Gab2) expression via miR-200c downregulation can promote epithelial-to-mesenchymal transition and CSC-like properties of ovarian cancer cells and enhance the metastatic growth of ovarian cancer in the xenograft model." (PMID 34946546, 2021).
ovarian carcinoma (continued). "GAB2 is upregulated in ovarian cancer cell lines compared to the ovary and HOSE cells." (PMID 33488950, 2020). "GAB2 is frequently amplified in ovarian cancer and is mostly correlated with serous histology type." (PMID 33488950, 2020). "Co-targeting the IKKβ and PI3K pathways downstream of GAB2 might be a promising therapeutic strategy for ovarian cancer." (PMID 31895688, 2020). "Co-targeting IKKβ and PI3K pathways downstream of GAB2 might be a promising therapeutic strategy for ovarian cancer that overexpresses GAB2." (PMID 26657155, 2016). "To further confirm whether GAB2-induced chemokines in ovarian cancer cells contribute to angiogenesis, we performed tube-formation assays using human umbilical vein endothelial cells (HUVECs) with matrigel." (PMID 26657155, 2016). "We next determined whether CXCL1, CXCL2 and CXCL8 were required for proliferation and survival of ovarian cancer cells with GAB2 overexpression." (PMID 26657155, 2016). "Together, these findings suggest that overexpression of GAB2 in ovarian cancers may contribute to upregulation of CXCL1, CXCL2 and CXCL8 expression in a context specific manner." (PMID 26657155, 2016). "Taken together, in consonance with previous observations, our results suggest that CXCL1, CXCL2 and CXCL8 could act as autocrine growth factors that directly promote proliferation and survival of ovarian cancer cells that overexpressed GAB2." (PMID 26657155, 2016). "In this study, we investigated the role of GAB2 overexpression in tumorigenesis of ovarian cancer." (PMID 26657155, 2016). "The expression of Gab2 predominantly regulates the migratory behaviors of ovarian cancer cells, and overexpression of Gab2 enhances migration and invasion, and downregulates the expression of E-cadherin in ovarian cancer cells with low baseline expression levels of Gab2." (PMID 26095858, 2015). "Genomic amplifications of Gab2 have been described in ~16% of ovarian carcinoma cases." (PMID 26095858, 2015). "Gab2 may be a potential target for the treatment of ovarian cancer." (PMID 37085900, 2023). "Notably, the OVCAR5 cell lines used in this study exhibit no ErbB3 signaling, and the TOV21G and lgrov-1 cells express low levels of ErbB3 protein, suggesting that the expression of erbB3 and Gab2 contribute to activation of the PI3K pathway in different subsets of ovarian cancer." (PMID 26095858, 2015). "Therefore, the Gab2 acted as ErbB3, which is important in ovarian cancer." (PMID 26095858, 2015). "Therefore we tested whether Gab2 mediates ascites-induced cell migration in ovarian cancer cells." (PMID 28881624, 2017). "To confirm these findings, we tested two additional previously published shRNAs targeting GAB2 (shGAB2 #6 and #7) or a control shRNA into FUOV1 cells and 2 additional ovarian cancer cell lines that also overexpressed GAB2 (NIH:OVCAR3 and IGROV1 cells)." (PMID 26657155, 2016). "Gab2 triggers epithelial-to-mesenchymal transition (EMT) and promotes the migration and invasion of ovarian cancer cells through activation of the phosphatidylinositol 3-kinase (PI3K) pathway." (PMID 26754532, 2016). "The novel Gab2/PI3K/Zeb1 pathway can be targeted by PI3K and mammalian target of rapamycin (mTOR) inhibitors and can be potentially used to treat Gab2-driven ovarian cancer in combination with standard chemotherapy." (PMID 26095858, 2015). "Recent study showed that Gab2 overexpression, via activation of the PI3K-ZEB1 pathway, promotes characteristics of EMT in ovarian cancer cells." (PMID 24816687, 2014). "Moreover, in the mechanical regulation of OSBPL members, a recent study showed that GAB2 and GAB3, co-expressed with the OSBPL gene family were interrelated with much-shorter progression-free survival in ovarian cancer." (PMID 34829830, 2021). "By contrast, conditioned media from ovarian cancer cells after GAB2 suppression failed to support tube formation of HUVECs." (PMID 26657155, 2016).
ovarian carcinoma (continued). "Overexpression of Gab2 reduced expression of E-cadherin and increased Zeb1 expression and cell migratory and invasive abilities through the activation of the PI3K pathway in ovarian cancer cells." (PMID 26356073, 2015). "GAB2 can activate CXCL8 and induce the expression of zinc-finger E homeobox-binding-1 (ZEB1) through the activation of the PI3K signaling pathway, which directly inhibits the transcription of E-cadherin, further promoting the migration and invasion of ovarian cancer cells." (PMID 37377954, 2023). "In addition, a previous study has reported that the overexpression of Gab2 activates the epithelial-mesenchymal transition program through activation of the PI3K/Zeb1 pathway, and inhibits the expression of E-cadherin in a subset of ovarian cancer." (PMID 26095858, 2015). "To examine whether high GAB2 levels in ovarian cancer cells are required for expression of CXCL1, CXCL2 and CXCL8, we suppressed GAB2 with inducible shRNAs in FUOV1 cells and observed that induced suppression of GAB2 decreased the mRNA levels of CXCL1, CXCL2 and CXCL8 compared with un-induced cells." (PMID 26657155, 2016).
Alzheimer disease (10 papers, 2009 to 2025). A progressive, neurodegenerative disease characterized by loss of function and death of nerve cells in several areas of the brain leading to loss of cognitive function such as memory and language. "GRB-associated binding protein 2 (GAB2) represents a compelling genome-wide association signal for late-onset Alzheimer’s disease (LOAD) with reported odds ratios (ORs) ranging from 0.75–0.85." (PMID 23724096, 2013). "Amongst the associations identified by this less stringent approach were those for brain levels of CLU, CR1 and GAB2 which were identified as risk loci in GWAS of Alzheimer's disease." (PMID 22685416, 2012). "In addition to the various neoplastic diseases, Gab2 is also increasingly implicated in Alzheimer's disease (AD)." (PMID 19737390, 2009). "GAB2 overexpression makes neurons vulnerable, increasing tau phosphorylation and leading to the Alzheimer’s disease phenotype." (PMID 39684694, 2024). "Findings of GWAS link a number of the identified genes to age-related disorders, such as GAB2 and late onset Alzheimer’s disease, and QKI and coronary heart disease/myocardial infarction." (PMID 31706268, 2019). "This region contains the GAB2 gene, a candidate gene for Alzheimer's disease and copy number variations in this region have also been linked with mental retardation." (PMID 21694764, 2011). "Interestingly, several upregulated DE genes were related to neurodegenerative diseases, such as genes related to Alzheimer’s disease: PSEN2, TREM2, and GAB2; Parkinson’s disease: ATP13A2 and DCTN1; and amyotrophic lateral sclerosis: TAF15 and FUS." (PMID 40877796, 2025). "Indeed, p97/Gab2 is required for the PI3K/AKT1 signaling pathway and p97/Gab2-mediated PI3K/AKT1 activation is involved in the pathogenesis of Alzheimer’s disease (AD) that shows the reduced GRIA1 surface expression." (PMID 32781725, 2020).